FRG1EP (FSHD region gene 1 family member E, pseudogene)
Gene: Transcribed unprocessed pseudogene on chromosome 20 (29,480,147 to 29,497,179, reverse strand). Ensembl gene ENSG00000282995.
Diseases named in the same sentence as FRG1EP in open-access papers:
FRG1EP is named in the same sentence as 2 diseases in open-access papers, as found by Europe PMC text mining. Sharing a sentence is not in itself a finding about the gene and the disease.
FRG1EP shares sentences with these, for which no sentence is quoted: cancer (1 paper); psychiatric diseases (1).